LATS2 (large tumor suppressor kinase 2)
Description:
Negative regulator of YAP1 in the Hippo signaling pathway that plays a pivotal role in organ size control and tumor suppression by restricting proliferation and promoting apoptosis. The core of this pathway is composed of a kinase cascade wherein STK3/MST2 and STK4/MST1, in complex with its regulatory protein SAV1, phosphorylates and activates LATS1/2 in complex with its regulatory protein MOB1, which in turn phosphorylates and inactivates YAP1 oncoprotein and WWTR1/TAZ. Phosphorylation of YAP1 by LATS2 inhibits its translocation into the nucleus to regulate cellular genes important for cell proliferation, cell death, and cell migration. Also phosphorylates YAP1 in response to cell contact inhibition-driven WWP1 ubiquitination of AMOTL2, which results in LATS2 activation. Acts as a tumor suppressor which plays a critical role in centrosome duplication, maintenance of mitotic fidelity and genomic stability. Negatively regulates G1/S transition by down-regulating cyclin E/CDK2 kinase activity. Negative regulator of the androgen receptor. Phosphorylates SNAI1 in the nucleus leading to its nuclear retention and stabilization, which enhances its epithelial-mesenchymal transition and tumor cell invasion/migration activities. This tumor-promoting activity is independent of its effects upon YAP1 or WWTR1/TAZ. Acts as an activator of the NLRP3 inflammasome by mediating phosphorylation of 'Ser-265' of NLRP3 following NLRP3 palmitoylation, promoting NLRP3 activation by NEK7.
Synonyms: KPM
Tractability: Small molecule: a high-quality ligand is known; it belongs to a druggable protein family. PROTAC: ubiquitination databases record sites on it; a small molecule that binds it is known.
Target class: Kinase; Enzyme; Protein Kinase; AGC protein kinase group; AGC protein kinase NDR family
Gene: Protein-coding gene on chromosome 13 (20,973,029 to 21,061,603, reverse strand). Ensembl gene ENSG00000150457.
Subcellular location: Cytoplasm, cytoskeleton, microtubule organizing center, centrosome; Cytoplasm; Cytoplasm, cytoskeleton, spindle pole; Nucleus
Subcellular location (Human Protein Atlas): Centriolar satellite; Cytosol
Pathways (Reactome):
Signal Transduction: Signaling by Hippo
Gene Ontology:
Molecular function: ATP binding; protein binding; protein serine kinase activity; protein serine/threonine kinase activity; protein kinase activity
Biological process: G1/S transition of mitotic cell cycle; hippo signaling; hormone-mediated signaling pathway; intracellular signal transduction; negative regulation of canonical Wnt signaling pathway; negative regulation of cell growth involved in contact inhibition; negative regulation of cyclin-dependent protein serine/threonine kinase activity; positive regulation of NLRP3 inflammasome complex assembly; protein phosphorylation; negative regulation of protein localization to nucleus; positive regulation of apoptotic process; regulation of organ growth; regulation of transforming growth factor beta receptor signaling pathway; mitotic cell cycle phase transition
Cellular component: cytoplasm; cytosol; nucleus; spindle pole; centrosome
Genetic constraint (gnomAD): Loss-of-function variants: 23 observed, 66.16 expected, observed/expected ratio (o/e) 0.35, 90% interval 0.25 to 0.49. The upper end of that interval is the gene's LOEUF score, 0.49, which puts it in group 2 of 6, group 1 being the genes least tolerant of losing a copy. Missense variants: 1,256 observed, 1,380 expected, observed/expected ratio (o/e) 0.91, 90% interval 0.87 to 0.95. Synonymous variants: 676 observed, 599.88 expected, observed/expected ratio (o/e) 1.13, 90% interval 1.06 to 1.2.
Cancer hallmarks: escaping programmed cell death (suppresses); invasion and metastasis (suppresses); genome instability and mutations (suppresses); invasion and metastasis (promotes); suppression of growth (promotes)
Homologues: Orthologues: chimpanzee LATS2 (99% identical), macaque LATS2 (97% identical), dog LATS2 (87% identical), rat Lats2 (83% identical), mouse Lats2 (82% identical), pig LATS2 (77% identical), guinea pig LATS2 (77% identical), rabbit LATS2 (76% identical), tropical clawed frog lats2 (72% identical), zebrafish lats2 (65% identical), Caenorhabditis elegans wts-1 (29% identical), Drosophila melanogaster dop (19% identical), and 4 more. Paralogues in human: LATS1 (53% identical), MAST2 (22% identical), MAST4 (21% identical), MAST3 (20% identical), MAST1 (20% identical), DMPK (15% identical), MASTL (13% identical), SGK1 (13% identical), SGK3 (11% identical), STK32C (11% identical), SGK2 (11% identical), STK32B (10% identical), and 1 more.
Diseases named in the same sentence as LATS2 in open-access papers:
LATS2 is named in the same sentence as 139 diseases in open-access papers, as found by Europe PMC text mining. Sharing a sentence is not in itself a finding about the gene and the disease. The quoted sentences say what the papers report.
breast carcinoma (50 papers, 2008 to 2025). "Our analysis showed that loss of one or more alleles of LATS1 or LATS2 is widespread amongst human breast cancers, with the most notable loss in the basal subtype." (PMID 36443313, 2022). "Hypermethylation of the LATS1 and LATS2 promoters is observed in 50% of breast cancers, whereas genomic loss of LATS1, LATS2, and NF2 also occurs in TNBC." (PMID 29562176, 2018). "Furthermore, the loss of heterozygosity of LATS1 and frequent copy number loss of LATS2 are often observed in breast cancer." (PMID 34831091, 2021). "Decreased LATS2 expression in breast cancer has been associated with promoter hypermethylation." (PMID 30456386, 2018). "Importantly, decreased expression of the LATS2L signature was correlated with reduced survival of luminal breast cancer patients; furthermore, low LATS2 mRNA was associated with decreased probability of relapse-free survival among lumB patients." (PMID 30456386, 2018). "Moreover, genes commonly down-regulated in LATS2L human lumB and Lats2-CKO PyMT tumors were also found significantly associated with worse outcome in luminal breast cancer." (PMID 30456386, 2018). "The Drosophila warts/lats gene is considered to be a tumor suppressor, and down regulation of LATS2 mRNA expression by promoter hypermethylation has been reported to be associated with several malignancies, including breast cancer, astrocytoma and acute lymphoblastic leukemia (ALL)." (PMID 20932276, 2010). "Finally, Lats2 has been shown down-regulated through promoter hypermethylation, in association with poor prognosis human breast cancers and acute lymphoblastic leukemia." (PMID 18800172, 2008). "Consistently, in breast cancer, LATS2 has been found to inhibit tumor growth and metastasis by negatively regulating the YAP/TAZ pathway." (PMID 39866229, 2025). "In conclusion, this study highlights the important role of exosomal miR-105-5p from breast cancer cells in promoting the transformation of NFs to CAFs and suggests that miR-105-5p-LATS2 is a potential target for the treatment of breast cancer." (PMID 40151143, 2025). "The E3 ligase SIAH2 was identified among the high peptide-spectrum matches (PSMs) and has been reported to regulate LATS2 in breast cancer." (PMID 38459604, 2024). "Later research found that miR-372 affected the expression of LATS2 in breast cancer cells by directly targeting its 3′-untranslated region." (PMID 37692482, 2024). "Despite LATS2 having been recognized as a target gene of CAFs-derived exosome microRNA-92 in breast cancer." (PMID 36727078, 2022). "Taken together, our results suggest that MIR22HG acts as a miR-629-5p sponge that can inhibit the proliferation and migration of breast cancer cells and stabilize LATS2 expression." (PMID 34446703, 2021). "After being absorbed by cancer cells, the miR-92 targets large tumor suppressor kinase 2 (LATS2) that interacts with Yes-associated protein 1 (YAP1) and regulates nuclear translocation of YAP1 in breast cancer cells." (PMID 34852849, 2021). "To identify the downstream targets of MIR22HG and miR-629-5p, we analyzed the breast cancer data from The Cancer Genome Atlas (TCGA) database and found that LATS2 expression was positively correlated with MIR22HG expression." (PMID 34446703, 2021). "Taking these into consideration, our results suggest that LATS2 also functions as a tumor suppressor in breast cancer and that miR-629-5p can promote the proliferation and migration of breast cancer cells by targeting LATS2 mRNA." (PMID 34446703, 2021). "The downregulation of LATS1 and LATS2 has been observed in astrocytoma, breast cancer, colon cancer, gliomas and non-small cell lung cancer, and is directly associated with a poor prognosis." (PMID 33411690, 2020).
breast carcinoma (continued). "It has been shown that LATS is a tumor suppressor in human cancer cells, and reduced expression of LATS1 or LATS2 can promote aggressive phenotype in human breast cancers." (PMID 33247672, 2020). "LATS2 has been mostly proved to be downregulated in human cancers including colorectal cancer, breast cancer, and hepatocellular carcinoma." (PMID 33414893, 2020). "And overexpression of LATS2 in breast cancer suppressed cell invasion through controlling tumor glucose metabolism." (PMID 33414893, 2020). "MiR-93 has been shown to increase proliferation, migration and invasion potential of MCF7 breast cancer cells and to have many potential targets involved in tumor growth, including the large tumor suppressor homologue 2 (LATS2)." (PMID 31581940, 2019). "Recent studies have shown that silencing of LATS2 expression promotes cellular invasion in breast cancer, while ectopic expression of LATS2 decreases cell invasion." (PMID 30046387, 2018). "Altogether, our findings imply that deregulation of LATS1 and LATS2 can exert both common and distinct effects on breast cancer progression, by interaction with a variety of regulatory pathways." (PMID 30456386, 2018). "We provide evidence that both LATS1 and LATS2 are bona fide tumor suppressors in an in vivo breast cancer setting." (PMID 30456386, 2018). "Overall, these findings demonstrate that deletion of Lats2 facilitates PyMT-driven tumorigenesis, further supporting the role of LATS2 as a tumor suppressor in human lumB breast cancer." (PMID 30456386, 2018). "Reduction of LATS2, as a tumour suppressor, in various cancers, including breast cancer, lung cancer and liver cancer was reported, which is consistent with our finding." (PMID 30046387, 2018). "For example, in breast cancer, LATS2 mRNA expression was downregulated by promoter hypermethylation and this alteration was associated with large tumour size, high rate of metastasis and estrogen receptor and progesterone receptor negativity." (PMID 30046387, 2018). "LATS2 co-localizes with ERα in the nucleus, and thus contributes to the resistance to tamoxifen and other ER antagonists in ER+ breast cancer." (PMID 30400599, 2018). "One such pathway is SREBF1 (also known as SREBP1), which is hyperactivated upon Lats2 depletion in both mammary tumors (ingenuity activation z-score 0.64; P-value of overlap 3.6 × 10−8) and mouse livers." (PMID 30456386, 2018). "Downregulation of LATS1 and LATS2 mRNA expression by promoter hypermethylation has been reported in breast cancer." (PMID 26942001, 2016). "It enhanced EC activities, including cell spreading and tube formation in a human breast carcinoma cell line by targeting the LATS2 gene (large tumour suppressor kinase 2), whereas it was found to be upregulated in human breast carcinoma tissues." (PMID 25197665, 2014). "In the present study, we found that exosomal miR-105-5p from breast cancer cells could be internalized into fibroblasts and transform NFs into CAFs by downregulating LATS2, leading to malignant positive feedback regulation between breast cancer cells and CAFs." (PMID 40151143, 2025). "In addition, the expression of LATS2 in breast cancer tissues was significantly lower than that in normal breast tissues." (PMID 40151143, 2025). "Similarly, the expression of LATS2 in breast cancer cells was also significantly lower than that in normal breast epithelial cells." (PMID 40151143, 2025). "Overall, their data suggest that the miR-135b/LATS2 axis could be a future therapeutic target for breast cancer." (PMID 37692482, 2024). "SIAH2 destabilizes LATS2 in breast cancer through hypoxia signaling." (PMID 38459604, 2024). "Therefore, the findings imply that miR-372, via targeting LATS2, acts as an oncogenic miRNA in breast cancer." (PMID 37692482, 2024).
breast carcinoma (continued). "Evidences have shown that the LATS2 promoter is usually hypermethylated in a variety of human tumours, such as lung cancer (~79%), breast cancer (~50%), and astrocytoma (~71%), implying an important role of LATS2 hypermethylation in regulating biological events in tumour cells." (PMID 35902569, 2022). "Finally, investigation of the biological function of LATS2 in breast cancer revealed that the siRNA-induced knockdown of LATS2 enhanced the proliferation and migration of breast cancer cells, indicating that LATS2 was also a tumor suppressor in breast cancer." (PMID 34446703, 2021). "Consistent with this notion, the loss of heterozygosity of LATS1 and frequent copy number loss of LATS2 has been reported in breast cancer, suggesting that partial but not complete inactivation of LATS kinases is important for breast cancer development." (PMID 34831091, 2021). "Therefore, our findings reveal the MIR22HG-dependent inhibition of breast cancer cell proliferation and migration via the miR-629-5p/LATS2 pathway, providing new insights and identifying novel therapeutic targets for breast cancer treatment." (PMID 34446703, 2021). "Together, these observations suggest that LATS2 is a tumor suppressor in lumB breast cancer." (PMID 30456386, 2018). "Moreover, we observed that LATS2 is required for induction of luminal breast cancer cell death by the PPARγ agonist RGZ." (PMID 30456386, 2018). "We examined the consequences of down-regulation of either LATS1 or LATS2 in breast cancer." (PMID 30456386, 2018). "Interestingly, luminal breast cancer patients with low expression of both LATS2 and PPARG displayed impaired overall survival, compared with patients with low LATS2 but high PPARG expression." (PMID 30456386, 2018). "LATS2 mRNA downregulation has been correlated with aggressive breast cancer and has been attributed to hypermethylated promotors; however, miRNA could be another mode of its regulation." (PMID 29203780, 2017). "Knockout of Lats1 and Lats2 increases proliferation of biliary epithelium and hepatoblasts, in contrast, overexpression of Lats1 reduces proliferation of human breast cancer cells MCF-7." (PMID 28257933, 2017). "Similarly, SIAH2 promotes tumour growth through downregulation of LATS2 in breast cancer cells and SIAH2 knockdown xenograft tumor growth is much suppressed." (PMID 27042197, 2016). "In a previous study, we demonstrated that under hypoxic conditions, HIF-1 increased transcription of the WWTR1 gene encoding TAZ and the SIAH1 gene encoding a ubiquitin ligase that triggers degradation of LATS2, a negative regulator of TAZ nuclear localization in breast cancer cells." (PMID 26059435, 2015). "Furthermore, exosomes from highly metastatic breast cancer cells contained much more miR-105-5p than those from poorly metastatic breast cancer cells and thus were more efficient at transforming NFs into CAFs through LATS2/NF-κB signaling." (PMID 40151143, 2025). "Besides, low levels of LATS2 mRNA could be a predictor for favorable response to epirubicin plus cyclophosphamide in breast cancers." (PMID 30400599, 2018). "Hence, the attenuated PPARγ signaling in LATS2-depleted breast cancer cells may account, at least in part, for the observed increase in glycolysis and the increased dependence on glucose for survival." (PMID 30456386, 2018). "Indeed, inhibition of DNA methylation by 5-aza-2′deoxycytidine (5-Aza) treatment increased the levels of LATS2 mRNA and protein in lumB-derived ZR75-1 cells, suggesting that lumB breast cancers might undergo selective pressure to silence LATS2 expression." (PMID 30456386, 2018). "In this study we used a genetic mouse model of basal-like breast cancer driven by epithelial-specific inactivation of the Hippo pathway-regulating LATS1 and LATS2 kinases to elucidate epithelial-stromal interactions." (PMID 39953252, 2025).